CXCL9 (C-X-C motif chemokine ligand 9)
Diseases named in the same sentence as CXCL9 in open-access papers (continued):
Sharing a sentence is not in itself a finding about the gene and the disease.
lymphoma (15 papers, 2013 to 2025). A malignant (clonal) proliferation of B- lymphocytes or T- lymphocytes which involves the lymph nodes, bone marrow and/or extranodal sites. "Case reports have described the expression of CXCL9 on lymphoma cells and its receptor CXCR3 on endothelial cells, as well as in other instances, such as CXCR4 expression on lymphoma cells and its ligand CXCL12 on the endothelium." (PMID 40723240, 2025). "In Alizadeh Lymphoma Statistics27, CXCL9 was found to be more highly expressed in DLBCL supported by Storz28, Rosenwald29, Compagno26, Brune30, and Basso31." (PMID 35181719, 2022). "It is reported that CXCL9 plays a significant role in lymphoma because of its chemotaxis on immunocytes." (PMID 27726306, 2016). "CXCL9 could also be of great importance for enhancing the understanding of metastasis of lymphoma." (PMID 27726306, 2016). "High expressions of CXCL9, along with CXCR3, were seen in thyroid and gastric marginal zone lymphoma and also mucosa associated lymphoid tissue type lymphoma, which were speculated to be associated with autocrine function and the migration of lymphoma cells." (PMID 24278236, 2013). "Among them, over-expressed CCL18, CCL19, CXCL9, CXCL10, and CXCL13 were listed in the top 20 deregulated genes in all lymphoma datasets." (PMID 35452413, 2022). "A few case reports described the presence of CXCL9 and CXCR3 17, as well as CXCL12 and CXCR4 18, on lymphoma cells and these CXC chemokines may serve as positive regulators for the lymphoma cells to aggregate in specific intravascular space." (PMID 24931821, 2014).
Arthritis (14 papers, 2007 to 2025). Inflammation of a joint. "Clinically, elevated CXCL9/CXCL10 levels have been detected in the serum of patients with ICI-induced arthritis and in lesional skin biopsies from those with immunotherapy-related dermatitis, directly linking this chemokine to irAE pathogenesis across organs." (PMID 40722787, 2025). "The only protective factor among those elicited by IL1β in ASCs is CXCL9, whose terminal peptide was studied as a therapeutic agent to ameliorate joint inflammation in a murine model of arthritis." (PMID 39202038, 2024). "CXCR3 ligands such as CXCL9 and CXCL10 also cause bystander T cell migration in the case of Lyme disease, causing inflammation in joints and arthritis." (PMID 36951943, 2023). "The pathological process of arthritis is also mediated by another gene, CXCL9, whose protein is detected in sera, synovial fluid, and synovial tissue." (PMID 36861127, 2023). "To further assess the severity of arthritis, we measured the mRNA levels of a variety of pro-inflammatory cytokines and chemokines, including Il18bp, Il18, Il1b, Il6, Il1r2, Ifng, Cxcl9, Cxcl1, and Cxcl2 in arthritic joints of IL-18BP KO and WT littermates." (PMID 37415987, 2023). "As the DA.Ncf1E3 congenic rats carry the arthritis-protecting variant of Ncf1, one might speculate that the effect caused by the functional Ncf1 is to generate a resistance to the effect from induction of Ass, Cxcl9 and Mmp12 genes, which might otherwise contribute to the development of arthritis." (PMID 17490473, 2007). "Additionally, miR-320a inhibits the progression of RA and its induction in MSC exosomes or its target, CXCL9 helped to attenuate arthritis and bone destruction in CIA mouse model." (PMID 33732263, 2021). "Using the flow cytometry-based, predesigned Human Chemokine CBA Kit, we detected higher levels of CCL2, CCL3, CCL4, CCL5, CXCL9, and CXCL10 in arthritis than in CTRL plasma." (PMID 28619088, 2017). "Taken together, clonotypes and trafficking analyses of T cells suggested that SF CXCR3hi CXCR6hi/lo effector CD8+ T cells, recruited via CXCL9/10/11 and CXCL16 secreted by myeloid cells, may contribute to arthritis-irAE disease pathogenesis." (PMID 35413951, 2022). "Indeed, it has been reported also that CXCL9 and CXCL10 act as macrophage chemoattractants in arthritis, chronic cardiac inflammation, and cancer, thus implicating these chemokines in inflammatory disease." (PMID 33510341, 2021). "Co-located chromosome 5 QTL controlling arthritis severity and humoral responses during B. burgdorferi infection were identified in the F2 intercross of C3H/HeNCr and C57BL/6NCr mice, confirming the involvement of the chemokine Cxcl9 gene in this model." (PMID 24505471, 2014). "We have previously shown that patients with antibiotic-refractory arthritis have significantly higher levels of proinflammatory cytokines and chemokines in SF, particularly IFN-γ and the IFN-inducible chemokines CXCL9 and CXCL10, than patients with antibiotic-responsive arthritis." (PMID 24286535, 2013).
Granuloma (14 papers, 2013 to 2025). A compact, organized collection of mature mononuclear phagocytes, which may be but is not necessarily accompanied by accessory features such as necrosis. "TNF is essential for the early induction of chemokines (e.g., CCL2, CCL3, CCL4, CXCL9–11) and for proper spatial organization of macrophages and lymphocytes in granulomas, thereby creating a protective pulmonary microenvironment." (PMID 40427602, 2025). "CXCL9 and MCP-3 have been shown to increase in blood in TB patients, whereas CCL19 has primarily been associated with granuloma formation and maintenance in mouse models of TB." (PMID 36561889, 2022). "The early-stage granulomas showed significantly upregulated expression compared to the control tissue, followed by a significant decrease in CXCL9 in early to advanced granulomas as lesions progressed." (PMID 33746980, 2021). "Histopathologic analysis of lesion tissues of CL patients show mixed granulomas consisting of macrophages, lymphocytes, epitheloid, and plasma cells; and chemokines such as CXCL-9, MCP-1, MIP-1α and MIP-1β are the potent chemoattractant of T cells, monocyte and macrophages." (PMID 24267152, 2013). "CXCL10 and CCL4 facilitate the migration of Th1 and CD8+ T cells to the granuloma (Soong, Henard and Melby, 2012), while CXCL9 recruits CD8+ T cells, Th1 cells, and NK cells, amplifying the immune response in granuloma areas." (PMID 40556761, 2025). "Increased expression of TNF, IFN-γ and IFN-γ RNA, as well as TNF-inducible chemokines CXCL9, CXCL10, and CXCL11, which are CXCR3 ligands, was shown in granuloma." (PMID 40427602, 2025). "Several chemokines, including CC motif chemokine ligand (CCL) 2, CCL18, CXC motif chemokine ligand (CXCL) 8, and CXCL9 are increased in the BAL fluid (BALF) of HP patients and contribute to the development of the cellular infiltrate and granulomas in HP." (PMID 39464896, 2024). "The production of CCL2, CXCL9, and CXCL8 modifies the type of tuberculous disease that a patient has, and they play a special role in the formation of granuloma." (PMID 32377537, 2020). "Previous studies indicated that IFNγ mediates expression and secretion of chemokines CXCL9, CXCL10, and CXCL11 in macrophages, resulting in the recruitment of CXCR3 bearing CD4+ Th cells and CD8+ Tc cells into the lung and granuloma formation in humans and mice." (PMID 39464896, 2024). "Increase in CXCR3 CD226 CD4 in sarcoidosis • CXCL9 and CXCL11 are ligands of CXCR3, are IFN-inducible and found in granulomas.• CXCR3 expressing CD4+ T cells are recruited in granuloma.B cells: more prevalent in the BAL of sarcoidosis and CTD-ILD patients compared to IPF." (PMID 39896815, 2024). "In mice models of granulomatous disease induced by Propionobacterium acnes, CXCL10 has been shown to be necessary for the formation of Th1 lymphocyte clusters in draining lymph nodes, and blockade of CXCR3 (the receptor for CXCL9 and CXCL10) and CCR5, inhibits the formation of granulomas in lungs." (PMID 24199653, 2013).
liver cancer (14 papers, 2016 to 2025). An epithelial or non-epithelial malignant neoplasm that arises from the liver. "Both results showed that CXCL9 expressions were independent risk factors in predicting the prognosis of liver cancer patients." (PMID 33854600, 2021). "Compared with the adjacent tumor tissue and most liver cancer cells lines, a significant increase expression of G6PD, CDCA8, and CTSC in HCC tissues and liver cancer cells was observed, whereas CXCL9 was significant downregulated." (PMID 38742112, 2024). "The ectopic expression of CXCL9 enhances migration, proliferation, and invasion of oral cavity squamous cell carcinoma cells and liver cancer cells in vitro." (PMID 32528301, 2020). "Ding et.al studied that the expression level of chemokine CXCL9 in CD133+ liver cancer cells was significantly elevated in the culture supernatants of direct co-culture with human umbilical vein endothelial cells by activating the NF-kB." (PMID 29050226, 2017). "Meanwhile, the MAPK pathways were screened and the ERK1/2 was found to be involved with the CXCR3-A and CXCL9 induced enhanced invasion of liver cancer cells." (PMID 26883105, 2016). "Previously, our team mainly focuses on the role of CXCL9 in liver diseases including hepatitis and liver cancer and found that CXCL9 is involved in them." (PMID 27738495, 2016). "In summary, we provided the evidence that CXCL9 binds to its receptor CXCR3-A to promote the metastasis of CD133+ liver cancer cells." (PMID 26883105, 2016). "In this research, although the results had exhibited that the CD133+ liver cancer cell adhesion ability was suppressed after co-cultured with CXCL9 for 24h through binding with CXCR3-A, the mechanism of it was not clarified." (PMID 26883105, 2016). "All the data indicated that the supernatants in the direct co-culture system promoted the metastasis of CD133+ liver cancer cells via the upregulated CXCL9 expression through the activation of NF-kB." (PMID 27738495, 2016). "Also, CXCR3-A suppressed the adhesion ability of CD133+ liver cancer cells that stimulated by CXCL9 for 24h." (PMID 26883105, 2016). "Moreover, in order to determine the impact of CXCL9 on the mobility of CD133+ liver cancer cells, the wound healing assay was performed." (PMID 26883105, 2016). "In the study, CXCR3-A isoform that was bound by CXCL9 was found to cause significant change of ERK1/2 phosphorylation level in the MAPK signaling pathway, consequently upregulating the MMP2 and MMP9 expression and promoting invasion and metastasis of CD133+ liver cancer cells." (PMID 26883105, 2016). "The analysis of TCGA liver cancer data showed that the expressions of AGFG1, IQGAP3, SPINK1, CXCL9, MYO1E, and POF1B were significantly increased in tumor tissues." (PMID 41578779, 2025). "The CXCR3-A isoform bound by CXCL9 upregulates MMP2 and MMP9 expression, and promotes invasion and metastasis of CD133(+) liver cancer cells." (PMID 31623313, 2019). "High expression of CXCL9 in the direct co-cultured supernatants played a significant role in enhancing the migration and invasion of CD133+ liver cancer cells." (PMID 27738495, 2016). "Furthermore, CXCL9 was identified to play a key role in the migration and invasion of CD133+ liver cancer cells." (PMID 27738495, 2016). "In addition, when the direct co-cultured supernatants were added with the neutralizing antibody of CXCL9, the enhanced migration and invasion abilities of CD133+ liver cancer cells were abolished." (PMID 27738495, 2016). "Above all, the results suggest that high CXCL9 release may play a key role in tumor TEM due to enhancing the migration and invasion abilities of the CD133+ liver cancer cells." (PMID 27738495, 2016). "In HBV-related HCC, the axis of HBx- (NF-kB)-(CXCL9/CXCR3-A)-pERK1/2-MMP2/MMP9 may play an important role in the invasion and migration of CD133+ liver cancer cells." (PMID 26883105, 2016). "Fortunately, we proved that CXCL9 could promote the invasion and migration of CD133+ liver cancer cells." (PMID 26883105, 2016).
liver cancer (continued). "In our previous study, it was identified chemokine CXCL9 that it could be upregulated by HBV protein X (HBx) through activating the nuclear factor-kappa B (NF-kB) and was able to promote the invasion of liver cancer cells." (PMID 26883105, 2016). "Among those, CXCL5, CXCL9, CXCL10, and CXCL11 were significantly elevated in patients with early HCC according to the Barcelona Clinic Liver Cancer (BCLC) stages 0/A compared to cirrhotic controls without HCC." (PMID 36982370, 2023).
Obesity (14 papers, 2015 to 2025). Accumulation of substantial excess body fat. "Elevated CXCL9 levels have been linked to reduced musculoskeletal and physical function, lower activity levels, and greater frailty in older adults, while exercise has been shown to lower CXCL9 and improve metabolic and immune parameters in obesity." (PMID 41301428, 2025). "Antibody-mediated neutralization of CXCL9 during established obesity conferred protection from hepatocellular damage, suggesting that activating the CXCL9 axis may represent an essential hallmark of MASLD progression." (PMID 40977717, 2025). "Inflammatory markers, including CD16, CD11c, CCR2, CCR5, TNF-α, IL-1β, IL-2, IL-12, CCL8, CCL19, and CXCL9, were positively correlated with IL-23 in the AT-compartment in the obesity context." (PMID 41158638, 2025). "The expression of CXCL9 was upregulated in NASH without fibrosis in a high-risk cohort of adults with obesity." (PMID 35514751, 2022). "This review provides an in-depth analysis of specific chemokines involved in the development of obesity, including C-C motif chemokine ligand 2 (CCL2), CCL3, CCL5, CCL7, C-X-C motif chemokine ligand 8 (CXCL8), CXCL9, CXCL10, CXCL14, and XCL1 (lymphotactin)." (PMID 39334887, 2024). "Examination of the fibroinflammatory effects of obesity in MMP14LKO mice revealed that both WD and HFFC feeding in mice increased hepatic inflammatory marker gene expression—TNFα, CXCL2, CXCL9, TGFβ, and IL-1β—in WT mice, and this was attenuated in WD-fed MMP14LKO mice." (PMID 39282008, 2024). "In our study, we found a positive correlation between CAV1 expression and CXCLs (CXCL9, CXCL10, and CXCL11); this could be explained by the proinflammatory role and heightened presence of CXCLs in obesity." (PMID 37048092, 2023). "At the same time, the expression of chemokines (Cxcl9, Cxcl10) and the chemokine receptor CXCR3, which are key for traffic to the tumor and extravasation, were highly down-regulated in obesity, suggesting that lower chemokine levels prevented effective recruitment of immune cells to the tumor site." (PMID 35103755, 2022). "MVMR further revealed that CXCL9, TNFSF12 (all-grade), and CCL25 (high-grade) exert BMI-independent effects, implicating direct immunomodulatory pathways rather than obesity-related inflammation." (PMID 40722787, 2025).
sarcoidosis (14 papers, 2013 to 2025). Sarcoidosis is a multisystemic disorder of unknown cause characterized by the formation of immune granulomas in involved organs. "While sarcoidosis fibroblasts also upregulated CXCL9 and CD74, they exhibited only modest increases in CCL5 and FN1." (PMID 39989459, 2025). "Moving on to biomarker analysis, our sarcoidosis cohort displays statistically significantly increased levels of granulomatous disease markers CXCL9 and CXCL10." (PMID 37445972, 2023). "For example, CXCL9, a chemoattractant for lymphocytes previously proposed as a marker of sarcoidosis severity, was also over-expressed in TB and is also dysregulated in Beryllium disease." (PMID 33276795, 2020). "Serum levels of CXCL9, CXCL10, and proteins associated with inflammation and/or disease activity (sIL2R, ACE, ESR and CRP) were measured in a prospective cohort of sarcoidosis subjects and controls." (PMID 24199653, 2013). "In IPF, CXCL9 serum levels are up-regulated compared to sarcoidosis and healthy control subjects." (PMID 39768150, 2024). "All our sarcoidosis patients had increased serum concentrations of CXCL9, CXCL10, CTO, and CCL18." (PMID 37445972, 2023). "Similarly, our prior whole blood gene expression data from sarcoidosis and control subjects confirmed that transcripts for CXCL10 were significantly more upregulated compared to CXCL9 in sarcoidosis (Gene Expression Omnibus, GSE19314)." (PMID 24199653, 2013). "CXCL10 and CXCL9 significantly correlated with sarcoidosis severity score." (PMID 24199653, 2013). "However, CXCL9 BALF levels are significantly higher in sarcoidosis patients than in IPF patients." (PMID 39768150, 2024). "Thus, individual sarcoidosis patients with higher circulating levels of CXCL10 compared to CXCL9 may have greater activation of the Type I and II interferon pathways, which we speculate could identify subsets of sarcoidosis phenotypes." (PMID 24199653, 2013). "One recent study by Ragusa in 2018 has reported high levels of Th1 dependent chemokines, MIG, CXCL9, and CXCR3 positive alveolar macrophages in BAL and biopsy samples of sarcoidosis patients." (PMID 38611622, 2024). "For example, CD103+CD4+ T-cells in BALF of sarcoidosis patients are lower than in other ILD, while some chemokines able to recruit T-helper lymphocytes, such as CXCL9, CXCL10, and CXCL11, are increased." (PMID 39062076, 2024). "Patients with ground-glass lesions are a seemingly biochemically specific subgroup of intrathoracic sarcoidosis, with increased levels of SAA, CXCL9, CXCL10, CCL18, CTO, and CA15.3." (PMID 37445972, 2023). "When comparing the entire sarcoidosis cohort with the healthy cohort, the values for all markers (SAA, CCL18, CA15.3, CXCL9, CXCL10, and CTO) statistically significantly differ (p-values ≤ 0.001), except for SP-D (p-value = 0.23)." (PMID 37445972, 2023). "Sarcoidosis fibroblasts also produced increased levels of chemoattractants (CCL2, CCL4, CCL5, CXCL9), suggesting a role in both maintaining T cell activation as well as in recruiting monocytes and T cells to the tissue microenvironment." (PMID 35668129, 2022). "Interrogation of the expression levels of these 10 sarcoidosis genes to TB and CM DEGs revealed CCL14, CXCL9, FABP4, NR1H3 were also significantly dysregulated in TB." (PMID 33276795, 2020). "Among those dysregulated transcripts, we validated 46 in TB and 44 in sarcoidosis, 14 of them differentially expressed in lung, 30 in lymph nodes and 4 genes dysregulated in both tissues ADAMST1, CXCL2, CXCL9, FABP4." (PMID 33276795, 2020). "We found statistically significant increases in CXCL9, CXCL10, and sIL2R in sarcoidosis subjects compared to control subjects." (PMID 24199653, 2013). "We previously identified up-regulated transcripts for interferon-inducible chemokines CXCL9, and CXCL10, in blood of sarcoidosis patients compared to controls." (PMID 24199653, 2013).